S100A8 (S100 calcium binding protein A8)
Diseases named in the same sentence as S100A8 in open-access papers (continued):
Sharing a sentence is not in itself a finding about the gene and the disease.
depression (4 papers, 2016 to 2023). "Studies have revealed a neuroinflammatory role of S100A8/A9 in various neurological and psychiatric disorders such as AD, Parkinson’s disease, depression, anxiety, MS, traumatic brain injury, and stroke." (PMID 35804434, 2022). "Whether other TLR2/4 ligands, such as S100A8/A9, exert pro-depression-like actions together with HMGB1 in the mPFC remains to be examined." (PMID 37443823, 2023). "Since S100A8 and S100A9 are involved in inflammation, which is related to depression, we selected them for validation by qRT‒PCR on individual samples from each participant, as opposed to proteomic analysis performed from a pool." (PMID 38049858, 2023). "SLE patients with depression or cognitive dysfunction as an ACR NPSLE manifestation had higher serum S100A8/A9 concentrations than non-NPSLE patients (median 1460 ng/ml, p = 0.007 and 1380 ng/ml, p = 0.013, respectively)." (PMID 35804434, 2022). "In our study, SLE patients with depression as an NPSLE manifestation according to the ACR model had higher S100A8/A9 concentrations in serum compared with non-NPSLE patients, supporting their suggestion of a pathogenetic contribution." (PMID 35804434, 2022). "However, SLE patients with the NPSLE manifestations “depression” or “cognitive dysfunction” had higher serum S100A8/A9 concentrations than non-NPSLE patients when applying the ACR model." (PMID 35804434, 2022).
diabetic foot ulcers (4 papers, 2023 to 2025). "Fig7B and 7C displays the expression levels of CCL20, CXCL13, FGFR2, FGFR3, PI3, PLA2G2A, and S100A8 across the six cell types.The results showed that the key pathogenic genes of diabetic foot ulcer were mainly involved in keratinocytes and neutrophils." (PMID 40749079, 2025). "Recent studies have implicated S100A8/A9 in the pathogenesis of various diabetic complications, such as diabetic retinopathy, diabetic foot ulcers, and diabetic atherosclerosis." (PMID 39624823, 2024). "Specifically, monocytes/macrophages increased expression of several apoptosis genes (including BCL2, FGFR3, FGFR1, CTH, CASP3, IL19, NME5, and S100A8/9) in diabetic foot ulcers compared to monocytes/macrophages in non-diabetic wounds." (PMID 38127424, 2023).
endometrial carcinoma (4 papers, 2022 to 2025). A malignant tumor arising from the epithelium that lines the cavity of the uterine body. "Larger prospective studies incorporating functional analyses are warranted to validate these findings and elucidate the mechanistic role of S100A8 in the progression and immune modulation of endometrial cancer." (PMID 41303754, 2025). "Fourth, functional analyses to clarify the mechanistic role of S100A8 in endometrial cancer progression were not performed." (PMID 41303754, 2025). "Although there have been studies linking S100A8, S100A11 as biomarker candidates for endometrial cancer detection, whether any other S100 gene family member is involved in endometrial carcinoma remains unclear." (PMID 35042454, 2022). "The absence of significant associations between tumor-intrinsic S100A8 expression (TPS and TI) and clinicopathological parameters in endometrial carcinoma may reflect its heterogeneous and context-dependent biology." (PMID 41303754, 2025).
head and neck cancer (4 papers, 2016 to 2024). A primary or metastatic malignant neoplasm affecting the head and neck. "The mRNA and protein expression levels of S100A8/A9 are decreased in head and neck cancers." (PMID 27297407, 2016).
Hypercholesterolemia (4 papers, 2013 to 2022). An increased concentration of cholesterol in the blood. "We used a high-fat/high-cholesterol diet in mice to study the effects of hypercholesterolemia over the alarmin S100A8 cascade in the hippocampus." (PMID 34449045, 2021).
hyperlipidemia (4 papers, 2013 to 2023). "In T2DM patients, chronic hyperglycemia and hyperlipidemia trigger the secretion of a damage-associated S100A8 molecule (calgranulin A) from pancreatic islets that in turn increase macrophage infiltration." (PMID 32793223, 2020). "Smoking and hyperlipidemia stimulate granulopoiesis and S100A8/A9 production." (PMID 24453429, 2013).
invasive ductal carcinoma (4 papers, 2017 to 2021). "S100A8 and S100A9 protein expression are also frequently detected in poorly differentiated invasive ductal carcinoma of breast cancer." (PMID 28051137, 2017).
Kawasaki disease (4 papers, 2018 to 2024). A rare inflammatory disease characterized by an acute febrile, systemic, self-limiting, medium-vessel vasculitis primarily affecting children. "Moreover, the monocyte marker genes S100A8 and S100A12 were enriched with larger weights on PANDA latent component 3 and were reported to exert proinflammatory functions in Kawasaki disease (KD) patients." (PMID 38798352, 2024). "Consistent with our findings, a study reveals that CM highly express S100A8, S100A9, and S100A12, IM express HLA-DQA1 and HLA-DPA1 and NCM mainly express CD16, demonstrating a distinct transcriptome across monocyte subsets in Kawasaki disease." (PMID 39318997, 2024).
myelodysplastic syndrome (4 papers, 2021 to 2023). A clonal hematopoietic disorder characterized by dysplasia and ineffective hematopoiesis in one or more of the hematopoietic cell lines. "In a recent study in patients with myelodysplastic syndrome, a closely related myeloid neoplasm with overlapping genetic alterations with MPN, the investigators observed altered expression of S100A8 in cases with epigenetic mutations." (PMID 37240094, 2023). "Furthermore, evidence suggests that downregulation of S100A8 restored erythroid lineage differentiation in a mouse model of myelodysplastic syndrome." (PMID 36906583, 2023). "Moreover, serum levels of S100A8 were significantly elevated in patients with myelodysplastic syndrome compared with healthy controls." (PMID 37146011, 2023).
myelofibrosis (4 papers, 2021 to 2024). A partial or complete replacement of the bone marrow stroma by fibrous tissue. "The hypothesis has already been validated in a JAK2-mutated murine model, in which the expression of S100A8/A9 heterocomplex provoked inflammation and promoted myelofibrosis, both of which could be reversible upon treatment with a small molecule targeting S100A8/A9 signaling inhibition." (PMID 37240094, 2023).
Neonatal sepsis (4 papers, 2017 to 2021). Systemic inflammatory response to infection in newborn babies. "Concentrations are so high that next to immunoregulatory functions S100A8/A9 in BM acts antimicrobially against important pathogens causing neonatal sepsis." (PMID 29326708, 2017). "To clarify the antimicrobial role of S100 proteins in BM, we assessed the activity of S100A8/A9 and S100A8 on the growth of three of the most common pathogens causing neonatal sepsis." (PMID 29326708, 2017). "The excessive release of S100A8/A9 or calprotectin in neonatal sepsis could be detrimental as it could exacerbate the inflammatory responses." (PMID 32076015, 2020). "Hence, the lower methylation levels observed in the promoters of genes involved in neutrophil activation (i.e., ATP8B4, LRG1, TREM1, PRTN3, S100A8, ELANE, and CD177) illustrates the role of DNAm in innate immunity in neonatal sepsis." (PMID 33659006, 2021). "However, in contrast to S100A8/A9, S100A8 did not inhibit the growth of any of the tested pathogens of neonatal sepsis (S. aureus, E. coli, and GBS), which is most likely due to the lack of transitional binding sites for divalent metal ions." (PMID 29326708, 2017).
nephritis (4 papers, 2017 to 2024). Inflammation of renal tissue. "In the ischemia-reperfusion-induced AKI mouse model, a specific subset of monocyte-derived macrophages marked by S100a8/S100a9 expression triggered and intensified kidney inflammation." (PMID 38770013, 2024). "The only significant difference in S100A8 levels in the serum, urine, and saliva was nephritis (serum, p = 0.012; urine, p = 0.015; and saliva, p = 0.003)." (PMID 35529863, 2022). "Among the clinical manifestations, nephritis was the most influential factor related to SLE in the concentration of S100A8 in serum, urine, and saliva." (PMID 35529863, 2022). "S100A8/9 protein expression has been shown to correlate with inflammatory activity on renal biopsy in patients with varied etiologies of nephritis." (PMID 29065913, 2017). "Perhaps the measurement of S100A8/A9 activity in the kidney itself, i.e., in the kidney biopsy, could contribute to determining the severity of nephritis in IgAV and/or its prognosis." (PMID 38672106, 2024). "Therefore, the measurement of serum S100A8/A9 levels cannot distinguish IgAV patients who have nephritis from those who have other clinical manifestations of the disease." (PMID 38672106, 2024).
pulmonary TB (4 papers, 2014 to 2024). "AUC, sensitivity, and specificity values of CXCL1, MMP8, and S100A8 are given for active pulmonary TB (ATB) vs pooled normal, ATB vs latent Mtb infection (LTBI) infection, and ATB vs non-TB comparisons." (PMID 34403447, 2021). "Several studies have shown that serum S100A8/A9 concentrations are increased in HIV-uninfected patients with pulmonary tuberculosis compared with controls, and that they are correlated with radiographic severity." (PMID 25107295, 2014). "Pulmonary TB is characterized by excessive inflammation, and we identified numerous inflammation-related proteins such as CRP, S100A8, and S100A9." (PMID 38512356, 2024). "In pulmonary TB, S100A9 contributes to neutrophil localization to granulomas, and both S100A8 and S100A9 are biomarkers of TB-related lung damage." (PMID 38861581, 2024).
rheumatic diseases (4 papers, 2020 to 2026). "The role of serum S100A8/A9 has been more comprehensively investigated in other rheumatic diseases." (PMID 38672106, 2024). "Similar correlations between serum S100A8/A9 levels and CRP, ESR, and ferritin were already established in other rheumatic diseases." (PMID 38672106, 2024). "Additionally, we identified the S100A8 subunit of calprotectin as a primary protein marker of interest for FSHD, consistent with its utility in numerous rheumatic diseases." (PMID 33228131, 2020).
rosacea (4 papers, 2011 to 2024). A chronic erythematous skin disorder that affects the face. "Our finding that S100A8, the mouse homologue for human S100A12, is increased in LL-37-injected skin suggests that S100 calgranulins also may have a prominent role in the cutaneous inflammation seen in patients with rosacea." (PMID 21347371, 2011).
Thrombocytosis (4 papers, 2020 to 2023). Increased numbers of platelets in the peripheral blood. "Clinical validation showed significantly enhanced S100A8 expression in CALRDEL-mutated MPN patients compared to CALRINS-mutated cases, and thrombocytosis was less prominent in those with S100A8 upregulation." (PMID 37240094, 2023). "The authors concluded that glycosylated hemoglobin, as well as increased plasma levels of S100A8/A9 correlate with reticulated thrombocytosis in DM-2 patients." (PMID 34065800, 2021). "Depleting neutrophils or Kupffer cells, or inhibiting S100A8/A9 binding to RAGE, reduced diabetes-induced thrombocytosis." (PMID 34065800, 2021).
acute leukemia (3 papers, 2017 to 2021). A clonal (malignant) hematopoietic disorder with an acute onset, affecting the bone marrow and the peripheral blood. "We demonstrated recently that S100A8 regulates differentiation of myeloid cells associated with acute leukemia, a disease characterized by overabundance of myeloid cell precursors and progenitors." (PMID 31437241, 2019). "Serum samples from CRMO patients contained higher concentrations of CCL4/MIP-1β, CCL5/RANTES, CCL11/eotaxin, S100A8, and lower concentrations of IL-18, sIL-2R, and osteoprotegerin when compared to samples from patients with acute leukemia." (PMID 29250517, 2017). "For de novo acute leukemia, antibodies targeting S100A8/A9 might be proposed for worse prognosis patients as MLL re-arranged ALL or height risk AML." (PMID 33801279, 2021). "Hence, the therapeutic targeting of S100A8 and S100A9 appears as a promising way to improve treatment efficiency in acute leukemias." (PMID 33801279, 2021). "Similarly, there are increasing data about the pathological role S100A8 and S100A9 play in the development of hematological malignancies and in particular in acute leukemias (AL)." (PMID 33801279, 2021). "Altogether, these data suggest that strategy targeting S100A8 and/or S100A9 might be fruitful at different stages of development of acute leukemia." (PMID 33801279, 2021). "Finally, a synthesis of the different therapeutic strategies targeting S100A8 and S100A9 and their potential in the treatment of acute leukemia is discussed." (PMID 33801279, 2021). "Hence, the therapeutic targeting of S100A8 and S100A9 appears to be a promising way to improve treatment efficiency in acute leukemias." (PMID 33801279, 2021).
anaplastic thyroid cancer (3 papers, 2015 to 2023). "In animal models, compared to controls, anaplastic thyroid carcinoma cells with S100A8 knockdown showed less lung metastasis and tumor load by tail vein injection, whereas S100A9 knockdown did not affect tumorigenesis and metastasis." (PMID 37701037, 2023). "Moreover, the inhibition of S100A8 proglycative function of S100A8 was proposed to be an appropriate therapeutic target in patients with anaplastic thyroid cancer." (PMID 34575195, 2021).
appendicitis (3 papers, 2012 to 2018). Acute inflammation of the vermiform appendix. "Our results showed that in many other diagnoses in the abdominal and pelvic areas as well as acute appendicitis, which accounts for most patients, the mean levels of the S100A8/A9 biomarker increase." (PMID 30057651, 2018).
atrial fibrillation (3 papers, 2021 to 2025). A disorder characterized by an electrocardiographic finding of a supraventricular arrhythmia characterized by the replacement of consistent P waves by rapid oscillations or fibrillatory waves that vary in size, shape and timing and are accompanied by an irregular ventricular response. "Many members of S100 family, including S100A8 and S100A9, have been involved in EMT in multiple types of cells: S100A4 was associated with expression of Snail in human cancers and atrial fibrillation." (PMID 34099591, 2021).
autoimmune uveitis (3 papers, 2016 to 2025). An autoimmune form of uveitis (disease). "S100A8, known to promote inflammatory cell migration and infiltration, has previously been associated with acute anterior uveitis and the recurrence of experimental autoimmune uveitis in animal models." (PMID 41402737, 2025). "Rats with experimentally induced autoimmune uveitis showed an increase in expression of S100A8 in the eye, and S100A8 blockade could be a therapeutic agent in this disease." (PMID 37372165, 2023). "Increased S100A8/A9 and S100A12 levels are found in the serum and aqueous humor of patients with autoimmune uveitis, and authors indicated that the serum levels reflect activity of joint and eye disease." (PMID 27786310, 2016).
candidiasis (3 papers, 2020 to 2021). Infection with the organism Candida. "We used a murine model of IAC to study the immunological contributions of S100A8/A9 during a clinically-relevant form of candidiasis." (PMID 33717058, 2021). "In lichen planus, candidiasis and other inflammatory diseases of the oral mucosa increased levels of S100A8/A9 were reported." (PMID 33420397, 2021). "Previous studies have identified the alarmins, S100A8 and S100A9, as key chemotactic mediators of the acute PMN response toward Candida infection." (PMID 33262741, 2020).
cholesteatoma (3 papers, 2014 to 2024). A pathologic process characterized by the proliferation of keratinizing squamous epithelium resulting in the accumulation of keratin and cells in the middle ear and/or mastoid. "It indicated that the levels of S100A8 and S100A9 were correlated with the severity of EACC based on Shin staging and Holt staging classification, supporting the potential pathogenic factors of S100A8 and S100A9 in cholesteatoma bone erosion." (PMID 39575241, 2024). "Notably, S100A8 and S100A9 are especially related to the severity of bone destruction caused by cholesteatoma based on Shin staging and Holt staging classification." (PMID 39575241, 2024). "Our data indicated the increased S100A8 and S100A9 were associated with increased IFN-γ and TGF-β but decreased IL-10 in clinical and animal models of EACC, consistent with the pathogenesis mechanism of inflammation involved in cholesteatoma pathogenesis." (PMID 39575241, 2024). "TLR4 signalling can also be induced by the DAMPs abundant in cholesteatoma tissue e.g. high-mobility group box 1 proteins (HMGB1), Tenascin, fibronectin, S100A8, S100A9 and also HSP60 and HSP70." (PMID 33627146, 2021). "The DNA chip analyses indicated that the S100A8 and S100A9 genes might be upregulated and involved in cholesteatoma pathogenesis." (PMID 39575241, 2024). "However, the role of S100A8 and S100A9 and their associated inflammatory and other signaling pathways in cholesteatoma have not been investigated yet." (PMID 39575241, 2024). "However, the role of S100A8 and S100A9 and their associated inflammation and other signaling pathways in cholesteatoma have not been investigated yet." (PMID 39575241, 2024).
chronic rhinosinusitis (3 papers, 2020 to 2023). Chronic form of sinusitis. "Richer and collaborators (2009) showed a decreased expression of S100A7, S100A8, S100A9, and SPINK5 genes in the airway mucosal epithelium of people with chronic rhinosinusitis, which they associated with a defective epithelial barrier in this condition." (PMID 32735560, 2020).
Cirrhosis (3 papers, 2009 to 2023). A chronic disorder of the liver in which liver tissue becomes scarred and is partially replaced by regenerative nodules and fibrotic tissue resulting in loss of liver function. "In the present study, the expression level of S100a10, S100a11, S100a6, S100a8 and S100a9 increased from cirrhosis to metastatic process when compared with the normal liver." (PMID 19638242, 2009). "Although the ratio of S100A8+ Mono/Mac (cluster Mono2) was decreased in the ACLF group, the absolute cell count of S100A8+ Mono/Mac was higher in the ACLF group compared with the HC and cirrhosis groups." (PMID 37380987, 2023).
colorectal adenocarcinoma (3 papers, 2014 to 2024). The most common type of colorectal carcinoma. "The Cancer Genome Atlas (TCGA) database mining of 592 colorectal adenocarcinoma patient cohort (COAD, Pan-Cancer Atlas/cBioPortal) consistently linked high expression of EC PECAM-1 and PMN/TAN S100A8 with poor prognosis and disease outcomes." (PMID 38329810, 2024).
dermatomyositis (3 papers, 2020 to 2023). Dermatomyositis (DM) is a type of idiopathic inflammatory myopathy characterized by evocative skin lesions and symmetrical proximal muscle weakness. "Enriched genes including S100A12, MPO (myeloperoxidase), S100A8, CXCL10, S100A9, CD244, CD244,and TLR7 have been linked to dermatomyositis." (PMID 38137330, 2023). "In ILD, serum S100A8/A9 levels are elevated in dermatomyositis (DM) patients with ILD compared with those in normal controls and are associated with ILD progression." (PMID 36077067, 2022).
E. coli infection (3 papers, 2012 to 2025). "Microarray assay of HUVEC cells treated with 10 μg/mL S100A8 revealed that ribosome pathway, pathogenic Escherichia coli infection pathway, apoptosis, and stress response genes were modulated by S100A8 treatment." (PMID 22685372, 2012). "Another main pathway negatively modulated by S100A8 treatment was pathogenic Escherichia coli infection (PECI)." (PMID 22685372, 2012).